TAS2R38 (taste 2 receptor member 38)
Diseases named in the same sentence as TAS2R38 in open-access papers (continued):
Sharing a sentence is not in itself a finding about the gene and the disease.
benign prostatic hyperplasia (1 paper, 2021). A non-cancerous nodular enlargement of the prostate gland. "In prostate cancer cell lines, TAS2R38 was significantly attenuated in two of three cell lines, while the expression pattern of the other investigated TAS2Rs was always diminished in relation to the expression level in a benign prostatic hyperplasia cell line (BPH1)." (PMID 34885005, 2021).
bipolar disorder (1 paper, 2025). A disorder of the brain that causes unusual shifts in mood, energy, activity levels and the ability to carry out day-to-day tasks. "This study highlights the potential impact of the TAS2R38 genotype on food preference, consumption, renal function, and bipolar disorder." (PMID 40498099, 2025).
chronic kidney disease (1 paper, 2025). Impairment of the renal function secondary to chronic kidney damage persisting for three or more months. "Additionally, we identified an association between the bitter sensitive allele and an increased risk of chronic kidney disease (OR = 1.020 [1.006, 1.035], p = 3.08 × 10–3), potentially suggestive of a role of TAS2R38 in kidney health and function." (PMID 40498099, 2025).
fatty liver (1 paper, 2019). "Besides the genes related to fatty liver, these findings may be linked to the ancestral Amerindian-derived risk alleles of the taste receptors TAS1R2, CD36, and TAS2R38 that are known to alter food preferences." (PMID 30608932, 2019).
gram-negative bacterial infections (1 paper, 2019). Infections caused by bacteria that show up as pink (negative) when treated by the gram-staining method. "In human upper airway, TAS2R38 is involved in detecting AHLs and plays a role in preventing Gram-negative bacterial infection, such as chronic rhinosinusitis." (PMID 31582750, 2019).
hay fever (1 paper, 2025). "Although the TAS2R38 genotype has previously been linked to respiratory tract conditions, we only found weak evidence for an association with respiratory illness or function, such as the risk of hay fever/rhinitis (OR = 1.021 [1.001, 1.041], p = 0.040)." (PMID 40498099, 2025).
head and neck cancer (1 paper, 2024). A primary or metastatic malignant neoplasm affecting the head and neck. "TAS2R expression, and particularly the TAS2R38 variants, has demonstrated prognostic value for sinonasal diseases, dental disease, otitis media, head and neck cancer, and thyroid cancer and dysfunction." (PMID 39317733, 2024).
Hypertension (1 paper, 2008). The presence of chronic increased pressure in the systemic arterial system. "Furthermore, a latitudinal cline was identified both for the allele frequencies of the SNPs associated with hypertension (CYP3A5, AGT, GNB3), as well as for those associated with the ability to taste phenylthiocarbamide (TAS2R38)." (PMID 18248681, 2008).
hyperthyroidism (1 paper, 2023). Overactivity of the thyroid gland resulting in overproduction of thyroid hormone and increased metabolic rate. "Additionally, the PAV/PVI diplotype showed higher total fat mass, and BMI median values comparing to the other TAS2R38 diplotypes in the sample, which could be related to its absence from the hyperthyroidism sample." (PMID 37432370, 2023). "In relation to hyperthyroidism, its predominance associated with PVV and/or AVV could be mainly due to the possibility of TAS2R38 expression in thyrocytes with lower sensitivity to antithyroid effects exerted by the exposition of individuals with these haplotypes to TAS2R38 agonists." (PMID 37432370, 2023).
intestinal cancer (1 paper, 2020). "Of note, TAS2R38 expression in the intestine is related to the risk of intestinal cancers associated with the taster/non-taster phenotype." (PMID 32019181, 2020).
nicotine dependence (1 paper, 2016). Physical and psychological dependence on nicotine. "TAS2R38 haplotypes have been hypothesized to influence smoking habits and nicotine dependence, since it has been shown that this gene has a lower expression in smokers, when compared to non-smoker individuals." (PMID 27711175, 2016). "For example, a study examining both African-American (AA) and European-American (EA) individuals found a significant association between TAS2R38 haplotypes and smoking, with the non-taster AVI haplotype being positively associated with smoking quantity and nicotine dependence." (PMID 27711175, 2016).
oral diseases (1 paper, 2022). "It was therefore appropriate to use these genotype results to further study the association between TAS2R38 genotypes and oral diseases." (PMID 35090440, 2022). "This study aimed to identify TAS2R38 polymorphisms among Thais and to explore any association between genotype and oral diseases." (PMID 35090440, 2022). "Thus, this study cannot be used to conclude that specific TAS2R38 genotypes cause or prevent oral diseases, but rather may be risk indicators to be considered in adult Thai patients." (PMID 35090440, 2022).
ovarian carcinoma (1 paper, 2021). A malignant neoplasm originating from the surface ovarian epithelium. "Interestingly, the expression of TAS2R38 was almost entirely below the limit of detection in all studied epithelial ovarian cancer cell lines, the ovarian cancer tissue and in HEC-1a." (PMID 34885005, 2021).
pancreatic ductal adenocarcinoma (1 paper, 2021). An infiltrating adenocarcinoma that arises from the epithelial cells of the pancreas. "Similarly, through a histological analysis of pancreatic ductal adenocarcinoma tissues, TAS2R38 was detected in 78% of the tissue samples, predominantly in cytoplasm and additionally associated with liposomes." (PMID 34885005, 2021).
periodontitis (1 paper, 2019). An acute or chronic inflammatory process that affects the tissues that surround and support the teeth. "From our study in mouse, it is plausible that TAS2R38 and downstream signaling molecules are also expressed in human gSCCs, presumably playing a similar role in regulating oral microbiota and protecting against periodontitis." (PMID 31582750, 2019).
polyp (1 paper, 2022). A usually exophytic mass attached to the underlying tissue by a broad base or a thin stalk. "In 15 patients (20.55%) from the study group, the expression of TAS2R38 was confirmed in both polyp and inferior turbinate mucosa." (PMID 35806350, 2022).
rheumatoid arthritis (1 paper, 2025). A chronic, systemic autoimmune disorder characterized by inflammation in the synovial membranes and articular surfaces. "TAS2R38 genotypes have been associated with the abundance of buccal bacterial species linked to rheumatoid arthritis." (PMID 41153757, 2025).
cancer (8 papers, 2016 to 2025). A tumor composed of atypical neoplastic, often pleomorphic cells that invade other tissues. "Literature on the relationship between cancer risk and TAS2R38 gene is inconsistent." (PMID 38687739, 2024). "On the other hand, the related tasting TAS2R38 genotypes and diplotypes were predominately linked to a lower cancer risk, suggesting a protective effect against bitter-tasting carcinogenic compounds for gastrointestinal types of cancer." (PMID 34885005, 2021). "Therefore, studying the genetic variations of the TAS2R38 is a promising approach to identify possible associations between bitterness perception and susceptibility to cancer, although the knowledge regarding cancer type specificity is limited." (PMID 34885005, 2021). "This diet-independent TAS2R38-cancer association may suggest that genetic variation in TAS2R38 involved in gastric carcinogenesis not simply via altered food intake but through other potential mechanisms." (PMID 27245112, 2016). "Therefore, the genetic variants of TAS2R38, by potentially modifying intake of these vegetables could impact cancer risk." (PMID 38687739, 2024). "TAS2R38 gene variants are associated with alterations in individual sensitivity to bitter taste and food intake; hence, these genetic variants may modify the risk for diet-related diseases, including cancer." (PMID 27245112, 2016). "In summary, the results from studies evaluating the association between the TAS2R38 and CA6 genes and the risk of cancer are inconsistent." (PMID 38687739, 2024). "Interestingly, these results were not reflected by analysing cancer incidence in relation to the diplotypes of TAS2R38." (PMID 34885005, 2021). "Furthermore, the genotype effect of TAS2R38 (PAV*) on various types of cancer can be weak/not detectable due to the fact that other factors may act as mediators between the TAS2R38 (AVI/AVI) and cancer." (PMID 38687739, 2024).
bacterial infection (5 papers, 2016 to 2025). "Very recently it could be demonstrated that persons with the TAS2R38 taster variant get less bacterial infections, because the bacterial components acyl-homoserine lactones (AHLs) activate these bitter taste receptors in upper respiratory epithelial cells." (PMID 26950109, 2016). "For TAS2R38, the AVI/AVI genotype was shown to be more susceptible to bacterial infection in ALI cultures." (PMID 40709685, 2025). "TAS2R38 is a crucial factor in protecting the sinonasal epithelium and has a role in bacterial infections of the respiratory system." (PMID 38397921, 2024). "So it might be possible that TAS2R38 in the placenta acts as a sensor for bacterial infection." (PMID 26950109, 2016).
infection (5 papers, 2021 to 2025). The state of being infected such as from the introduction of a foreign agent such as serum, vaccine, antigenic substance or organism. "rs1726866, a missense variant (Val 262 Ala) in TAS2R38, was associated with infection in individuals with respiratory disease (OR: 1.86; CI: 1.22, 2.88; p = 0.004)." (PMID 41153757, 2025). "To achieve this goal, we analyzed the effect of SARS-CoV-2 on the methylation status of CpG sites associated with TAS2R38 during infection and after the cessation of the exposition to the virus, also considering the disease severity and the TAS2R38 genotype of participants." (PMID 40280971, 2025). "We analyzed the effect of SARS-CoV-2 on the methylation pattern of TAS2R38 (at cg25481253, a CpG site located in the coding region) during infection and after the cessation of the exposure to the virus, also considering the disease severity and TAS2R38 SNPs." (PMID 40280971, 2025). "In this study, we aimed to investigate whether PCD subjects are more susceptible to infection by SARS-CoV-2 and whether some polymorphisms of the TAS2R38 bitter taste receptor correlate with an increased prevalence of SARS-CoV-2 infection and severity of symptoms." (PMID 39201321, 2024).
neoplasm (4 papers, 2020 to 2026). A benign or malignant tissue growth resulting from uncontrolled cell proliferation. "A meta-analysis of the studies detailly described herein could not find any associations between the common genetic variations within the TAS2R38 gene and the risk for neoplasm along the gastrointestinal tract." (PMID 34885005, 2021). "The hub gene ADCY6, CXCL3, NPBWR1, TAS2R38, and PTGDR2 highly influence the clinical traits of age, histology types, neoplasm histologic grade, and overall survival in ESCA and READ, leading to their similarity in these clinical traits." (PMID 33552958, 2020). "TAS2R38 was found in tumour-infiltrating leukocytes as well, but not in non-cancerous pancreatic cells of the tissue samples." (PMID 34885005, 2021).
respiratory disease (2 papers, 2017 to 2025). "Because of the role that biofilms play in the pathogenesis of recalcitrant respiratory disease, which has been directly correlated with TAS2R38 genotype, it is likely that broader conclusions may be drawn about local immune responses at diverse sites throughout the body." (PMID 28218655, 2017).
TAS2R38 also shares sentences with these, for which no sentence is quoted: cardiovascular disease (2 papers); metabolic disease (2); sinusitis (2); Alcohol Use Disorders (1); Alzheimer disease (1); Anorexia (1); anorexia nervosa (1); Anxiety (1); Blindness (1); dementia (1); depression (1); dysmenorrhoea (1); eating disorder (1); inflammatory skin disease (1); metabolic syndrome (1); morbid obesity (1); neurodegenerative disease (1); nonalcoholic fatty liver disease (1); otitis media (1); Parkinson disease (1); prostate carcinoma (1); pulmonary edema (1); rhinitis (1); skin melanoma (1); thyroid cancer (1); type 2 diabetes (1); upper respiratory tract infection (1).